ST6GALNAC1 (ST6 N-acetylgalactosaminide alpha-2,6-sialyltransferase 1)
Description:
Protein sialyltransferase specifically expressed in goblet cells that plays a key role in intestinal host-commensal homeostasis. Conjugates sialic acid with an alpha-2-6 linkage to N-acetylgalactosamine (GalNAc) glycan chains linked to serine or threonine in glycoproteins. Catalyzes the formation of the sialyl-Tn (S-Tn) antigen, an antigen found in intestinal goblet cells, as well as ulcerative colitis (UC) and various cancers. Protein sialylation in globlet cells is essential for mucus integrity and is required to protect the intestinal mucus against excessive bacterial proteolytic degradation.
Synonyms: ST6GalNAcI; SIAT7A; HSY11339; STYI
Tractability: Antibody: UniProt predicts a signal peptide or a membrane-spanning region.
Gene: Protein-coding gene on chromosome 17 (76,624,756 to 76,643,812, reverse strand). Ensembl gene ENSG00000070526.
Subcellular location: Golgi apparatus membrane
Subcellular location (Human Protein Atlas): Golgi apparatus; Nucleoplasm
Pathways (Reactome):
Metabolism of proteins: Sialic acid metabolism
Gene Ontology:
Molecular function: alpha-N-acetylgalactosaminide alpha-2,6-sialyltransferase activity; protein binding; sialyltransferase activity
Biological process: glycoprotein biosynthetic process; host-mediated modulation of intestinal microbiota composition; oligosaccharide biosynthetic process; carbohydrate derivative biosynthetic process; host-mediated perturbation of symbiont process
Cellular component: Golgi membrane
Genetic constraint (gnomAD): Loss-of-function variants: 45 observed, 57.96 expected, observed/expected ratio (o/e) 0.78, 90% interval 0.61 to 1. The upper end of that interval is the gene's LOEUF score, 1, which puts it in group 4 of 6, group 1 being the genes least tolerant of losing a copy. Missense variants: 743 observed, 772.77 expected, observed/expected ratio (o/e) 0.96, 90% interval 0.9 to 1.02. Synonymous variants: 295 observed, 303.92 expected, observed/expected ratio (o/e) 0.97, 90% interval 0.88 to 1.07.
Homologues: Orthologues: chimpanzee ST6GALNAC1 (99% identical), macaque ST6GALNAC1 (95% identical), pig ST6GALNAC1 (70% identical), guinea pig ST6GALNAC1 (70% identical), dog ST6GALNAC1 (64% identical), rabbit ST6GALNAC1 (62% identical), mouse St6galnac1 (58% identical), rat St6galnac1 (58% identical), zebrafish st6galnac1.1 (29% identical), tropical clawed frog ST6GALNAC1 (26% identical), zebrafish st6galnac1.2 (26% identical). Paralogues in human: ST6GALNAC2 (24% identical), ST3GAL4 (14% identical), ST3GAL1 (14% identical), ST6GAL2 (14% identical), ST3GAL2 (13% identical), ST3GAL3 (13% identical), ST3GAL5 (12% identical), ST3GAL6 (12% identical), ST6GAL1 (12% identical), ST6GALNAC5 (11% identical), ST6GALNAC4 (10% identical), ST6GALNAC6 (9% identical), and 2 more.
Diseases named in the same sentence as ST6GALNAC1 in open-access papers:
ST6GALNAC1 is named in the same sentence as 33 diseases in open-access papers, as found by Europe PMC text mining. Sharing a sentence is not in itself a finding about the gene and the disease. The quoted sentences say what the papers report.
breast carcinoma (11 papers, 2009 to 2024). "Upregulation of ST6 N-acetylgalactosaminide alpha-2,6-sialyltransferase 1 (ST6GALNAC1) has been associated with good prognosis in breast cancer." (PMID 31337362, 2019). "In breast cancer, the expression of RNA encoding ST6GalNAc1 correlates with sialyl-Tn expression." (PMID 27754373, 2016). "Expression of ST6GalNAc1 in gastric and breast cancer cell lines also leads to reduced cell adhesion and increased cell motility, similar to what we observe in the prostate." (PMID 26452038, 2015). "Expression of ST6GalNAc1 in gastric and breast cancer cell lines induces the sTn antigen and leads to reduced cell adhesion and increased cell motility, similar to what we observe in the prostate." (PMID 26452038, 2015). "Meta-analysis of ST6GalNAc1 expression in colon and breast cancer tissue versus normal tissue shows significant down-regulation in 6/8 datasets for primary colon cancer, and in 4/8 datasets for primary breast cancer, the opposite of what we see in PCa." (PMID 26452038, 2015). "Overexpression of ST6GALNAC1 in the MDA-MB-231 breast cancer line has also been shown to promote the invasion and migration of breast cancer cells via the EMT pathway while higher levels of ST8SIA4 promote tumorigenicity in the same cancer cell line." (PMID 39628991, 2024). "In addition, overexpression of ST6GalNAc1 that promotes STn type glycans on MUC1, increased intraperitoneal metastasis of human gastric cancer cells and led to increased growth of human breast cancer cells in immunodeficient mice." (PMID 27754373, 2016).
gastric cancer (9 papers, 2014 to 2022). A primary or metastatic malignant neoplasm involving the stomach. "Hidenori Ozaki elucidated the roles of ST6GalNAc-1 by in vivo monitoring system in gastric cancer metastasis." (PMID 29423033, 2018). "ST6GALNAC1 is a member of the sialyltransferase family of molecules, which was reported as overexpressed in several cancers, including gastric cancer, and as correlated with cancer metastasis." (PMID 27681076, 2016). "Human gastric cancer cells with enhanced ST6GalNAc1 expression showed higher intraperitoneal metastasis compared to sTn-negative tumor cells." (PMID 24592356, 2014). "Additionally, siRNA-mediated silencing of ST6GALNAC1 has been shown to lead to reduced growth, migration and invasion of gastric cancer cells in vitro." (PMID 31337362, 2019).
prostate carcinoma (9 papers, 2015 to 2024). A carcinoma that arises from epithelial cells of the prostate gland. "In prostate cancer cells, an alternative spliced ST6GALNAC1 mRNA isoform that encodes a shorter ST6GalNac1 protein isoform is made." (PMID 28382513, 2017). "ST6GalNAc1 is frequently upregulated concurrently with another important glycosylation enzyme GCNT1 previously associated with prostate cancer progression and implicated in Sialyl Lewis X antigen synthesis." (PMID 26452038, 2015). "It was also found that the expression of ST6GALNAC1 in prostate cancer cells changes global gene expression profiles toward mesenchymal-like pattern increasing cell mobility and decreasing cell adhesion." (PMID 31447885, 2019). "ST6GALNAC1 gene is directly activated by androgens and is frequently overexpressed in prostate cancer." (PMID 31447885, 2019). "This shorter ST6GalNac1 protein is produced at higher levels in prostate cancer cells than the previously reported full-length protein; yet it is able to synthesise the sTn antigen which is linked to patient survival and metastasis, and controls cell adhesion." (PMID 28382513, 2017). "In this study we confirm androgen regulation of ST6GalNAc1 and show for the first time a link between androgens and two additional O-glycosylation enzymes in prostate cancer, GALNT7 and GCNT1." (PMID 27428423, 2016). "Analysis of publically available RNA-Seq data show that ST6GalNAc1 exon 2 is detected in both clinical prostate cancer and in a number of additional cancers, particularly lung cancer." (PMID 26452038, 2015). "We found ST6GalNAc1 mRNA was significantly up-regulated in prostate carcinoma relative to BPH tissue (p = 0.048), and in primary prostate tumour tissue relative to matched normal tissue from the same patient (p < 0.04)." (PMID 26452038, 2015). "Here we show that expression of the sialyltransferase enzyme ST6GalNAc1 is directly activated by androgens in prostate cancer cells." (PMID 26452038, 2015). "We found that 6/7 datasets showed significant up-regulation of ST6GalNAc1 mRNA expression in prostate carcinoma versus normal prostate tissue." (PMID 26452038, 2015). "To examine if expression of the ST6GalNAc1 gene becomes changed in clinical prostate cancer we carried out meta-analysis of 544 prostate tumours using data from 7 previously published studies." (PMID 26452038, 2015). "Our results show for the first time that expression of sTn is induced by androgens in prostate cancer cells and that this is mediated by ST6GalNAc1." (PMID 26452038, 2015). "Meta-analysis of clinical RNA-Seq datasets show that although ST6GalNAc1 expression is up-regulated in primary prostate carcinoma, expression is relatively reduced in metastatic prostate tissue." (PMID 26452038, 2015). "ST6GalNAc1 has a dynamic expression pattern in clinical datasets, being significantly up-regulated in primary prostate carcinoma but relatively down-regulated in established metastatic tissue." (PMID 26452038, 2015). "The retinoblastoma tumor suppressor gene RB1 is more commonly mutated in metastatic and ADT-recurrent prostate cancer than in primary tumors, while the expression of the ST6GalNAc1 gene is upregulated in primary prostate cancer cells and repressed in patients undergoing androgen deprivation therapy." (PMID 32872551, 2020). "Confirming that this short protein is the major ST6GalNAc1 protein isoform expressed in clinical prostate cancer, the 55KDa ST6GalNAc1 protein isoform was also detected in androgen-treated VCaP cells, and in clinical prostate samples by western blot analysis in 5 out of 5 tissue lysates." (PMID 26452038, 2015). "Of 31 reciprocally-regulated glycosylation enzymes, a set of 8 (GALNT7, ST6GalNAc1, GCNT1, UAP1, PGM3, CSGALNACT1, ST6GAL1 and EDEM3) were significantly up-regulated in clinical prostate carcinoma." (PMID 27428423, 2016).
prostate carcinoma (continued). "Furthermore, authors revealed such genes for the TMPRSS2-ERG prostate cancer molecular subtype (B4GALNT4, ASRGL1, MYBPC1, RGS11, SLC6A14, GALNT13 and ST6GALNAC1)." (PMID 36077746, 2022). "Additionally, we revealed such genes for the TMPRSS2-ERG prostate cancer molecular subtype (B4GALNT4, ASRGL1, MYBPC1, RGS11, SLC6A14, GALNT13, and ST6GALNAC1)." (PMID 31447885, 2019). "Surprisingly, we find that rather than the canonical 69 KDa isoform of ST6GalNAc1, a novel ∼55KDa protein isoform of the ST6GalNAc1 protein isoform is instead induced by androgens in prostate cancer cell lines in vitro, and also expressed in clinical prostate tissue." (PMID 26452038, 2015).
lung carcinoma (8 papers, 2015 to 2025). "The sensitivity and specificity of CLCA2, SPATS2, ST6GALNAC1, and Adipophilin in adequate subtyping of poorly differentiating lung cancer and reaching accurate diagnosis was 100%." (PMID 33936227, 2021). "The combination of biomarkers of CLCA2, SPATS2, ST6GALNAC1, and Adipophilin may lead to an appropriate subtyping of lung cancer and reaching accurate diagnosis with the highest sensitivity and specificity." (PMID 33936227, 2021).
colon carcinoma (5 papers, 2015 to 2022). "N-acetylglucosaminyltransferase-V (GnT-V) and ST6 N-Acetylgalactosaminide alpha-2,6-Sialyltransferase 1 (ST6GALNAC1) facilitated glycosylation have been reported to control stemness of colon cancer cells through WNT signaling and Akt pathway respectively." (PMID 33889547, 2021). "Several studies have suggested that ST6GalNAc1 is overexpressed in breast and colon cancer, and upregulation of ST6GalNAc1 promotes tumor growth and metastasis." (PMID 32522293, 2020). "Since ST6GalNAc1 expression has been shown to increase establishment of metastases in breast and colon cancer, we next examined tumour cell dissemination by injecting DU145 cells tagged with Gaussia luciferase (G-Luc) intravenously." (PMID 26452038, 2015). "Since expression of ST6GalNAc1 increases tumour mass in breast and colon cancer, we analysed the effect of ST6GalNAc1 on prostate tumourigenesis using in vivo models." (PMID 26452038, 2015). "The canonical 69KDa ST6GalNAc1 protein isoform is the major previously reported isoform in breast and colon cancers where it has been well-studied." (PMID 26452038, 2015). "However, in breast and colon cancer over-expression of ST6GalNAc1 has been shown to increase both tumour growth and metastatic ability, which was not seen here in PCa cells." (PMID 26452038, 2015). "Our data suggests that unlike in breast and colon cancer, over-expression of ST6GalNAc1 in PCa cells reduces tumour growth and does not affect metastasis." (PMID 26452038, 2015).
ovarian carcinoma (4 papers, 2015 to 2021). A malignant neoplasm originating from the surface ovarian epithelium. "There are few studies on the effects that ST6GALNAC1 has on ovarian cancer; therefore, the differential expression of ST6GALNAC1 in ovarian cancer and possible molecular mechanisms were investigated in this present study." (PMID 30996686, 2019). "In this current study, it was shown that ST6GALNAC1 was overexpressed in ovarian cancer cell lines and OCSCs." (PMID 30996686, 2019). "The expression profile of ST6GALNAC1 in GSE18520 and GSE66957 chips was extracted and ST6GALNAC1 was abnormally highly-expressed in ovarian cancer in GSE18520 and GSE66957 chips." (PMID 30996686, 2019). "In conclusion, the present study suggests that ST6GALNAC1 activates the biological characteristics of OCSCs in ovarian cancer, which is achieved through increased proliferation, invasion and migration of OCSCs via activation of the Akt signaling pathway." (PMID 30996686, 2019). "For example, the top hub gene in the network was ST6GALNAC1 which is known to have an important role in ovarian cancer." (PMID 26138921, 2015). "Indeed, overexpression of ST6GalNAc1 in gastric, breast, prostate and ovarian cancer cell lines and tissues has shown to induce the expression of the sTn antigen." (PMID 34975914, 2021). "After that, levels of ST6GALNAC1 in OCSCs and ovarian cancer cells were examined." (PMID 30996686, 2019). "This present study aims to investigate how ST6GALNAC1 affects ovarian cancer stem cells (OCSCs)." (PMID 30996686, 2019). "It is highly possible that ST6GALNAC1 may affect biological characteristics of ovarian cancer stem cells (OCSCs) via the Akt signaling pathway." (PMID 30996686, 2019). "Furthermore, ST6GalNAc1 activity might foster cancer cell stemness, as expression of CSC markers and tumor sphere formation capability were increased in ST6GalNAc1 overexpressing colorectal or ovarian cancer cell lines." (PMID 34975914, 2021). "Therefore, it was speculated that ST6GALNAC1 was abnormally expressed in ovarian cancer and may mediate the Akt signaling pathway." (PMID 30996686, 2019). "Therefore, in this present study, the aim was to investigate the role of ST6GALNAC1 in the occurrence and development of ovarian cancer and whether ST6GALNAC1 functioned through the Akt signaling pathway." (PMID 30996686, 2019).
bladder cancer (3 papers, 2017 to 2021). "In high grade bladder cancer tissues, the significant overexpression of sTn antigen is associated with increased expression of ST6GALNAC1 sialyltransferase and down-regulates anti-cancer immune response through different mechanisms." (PMID 32596162, 2020). "The sialyl-Tn (sTn) antigen is an O-linked carbohydrate chain aberrantly expressed in bladder cancer (BC), whose biosynthesis is mainly controlled by the sialyltransferase ST6GALNAC1." (PMID 28903359, 2017). "An α2,6 sialyl acyltransferase ST6GALNAC1 was found to be overexpressed in bladder cancer tissues with higher malignancy, and this change is related to the sTn antigen, which is also explained above." (PMID 32596162, 2020). "Another sialylated glycan in bladder cancer is sTn, which is usually produced by overexpression of ST6GALNAC1 sialyltransferase." (PMID 32596162, 2020).
lung adenocarcinoma (3 papers, 2021 to 2025). A carcinoma that arises from the lung and is characterized by the presence of malignant glandular epithelial cells. "Several studies have indicated enhanced expression of ST6GALNAC1 in several cancer tissues, including lung adenocarcinoma (LUAD), lung squamous cell carcinoma (LUSC), and clear-cell renal cell carcinoma (ccRCC) samples." (PMID 39348343, 2024).
prostate tumours (3 papers, 2015 to 2024). "The data presented above suggests that expression of ST6GalNAc1 mRNA is significantly up-regulated in primary prostate tumours relative to normal prostate gland." (PMID 26452038, 2015). "Hence, 95.7% (67 out of 70) of primary prostate tumours with up-regulated ST6GalNAc1 mRNA also had up-regulation of at least one other glycosylating enzyme (Z score v normal +/− 1.6)." (PMID 26452038, 2015).
adenoma (1 paper, 2021). A neoplasm arising from the epithelium. "A bioinformatics study on CRC showed differentially expressed SLITRK6 together with L1TD1 and ST6GALNAC1, and it was downregulated in CRC compared to adenomas using microarray expression analysis." (PMID 33670246, 2021).
allergic conjunctivitis (1 paper, 2023). "However, the lengths of the pollen aggregates were smaller, and the eosinophilic inflammation upon induction of allergic conjunctivitis was exacerbated in St6galnac1 KO mice compared to those in WT mice." (PMID 36932081, 2023).
aneurysm (1 paper, 2021). Bulging or ballooning in an area of an artery secondary to arterial wall weakening. "Furthermore, our Pearson correlation analysis showed that some of genes (namely, ST6GALNAC1, TIFAB, and CCDC85B) may be informative in assessing IA risk, as their intraluminal expression was related to aneurysm size, IA wall enhancement, or both." (PMID 34441376, 2021).
Arthritis (1 paper, 2020). Inflammation of a joint. "Finally, we identify ST6GALNAC1 as a marker of undifferentiated arthritis and MSA4A, PDZK1IP1 and EPHB2 whose expression profiles may potentially discriminate untreated early RA from UA and SLA." (PMID 32483203, 2020).
meningioma (1 paper, 2024). A generally slow growing tumor attached to the dura mater. "In the GEO database, mRNA expression of ST3GAL4 was significantly decreased in grade II and III meningiomas (P < 0.05), while the others (ST3GAL1, ST3GAL3, ST3GAL6, ST6GAL1, and ST6GALNAc1) were not." (PMID 38274327, 2024).